PTBP2 (polypyrimidine tract binding protein 2)
Description:
RNA-binding protein which binds to intronic polypyrimidine tracts and mediates negative regulation of exons splicing. May antagonize in a tissue-specific manner the ability of NOVA1 to activate exon selection. In addition to its function in pre-mRNA splicing, plays also a role in the regulation of translation. [Isoform 5]: Reduced affinity for RNA.
Synonyms: NPTB; PTB; PTBLP; brPTB
Tractability: PROTAC: ubiquitination databases record sites on it; its protein half-life has been measured.
Gene: Protein-coding gene on chromosome 1 (96,721,573 to 96,823,738, forward strand). Ensembl gene ENSG00000117569.
Subcellular location: Nucleus
Subcellular location (Human Protein Atlas): Nucleoplasm
Gene Ontology:
Molecular function: RNA binding; mRNA binding; nucleic acid binding
Biological process: negative regulation of RNA splicing; cerebellum development; mRNA processing; spinal cord development
Cellular component: nucleus; growth cone; neuronal cell body; spliceosomal complex
Genetic constraint (gnomAD): Loss-of-function variants: 12 observed, 46.29 expected, observed/expected ratio (o/e) 0.26, 90% interval 0.17 to 0.42. The upper end of that interval is the gene's LOEUF score, 0.42, which puts it in group 1 of 6, group 1 being the genes least tolerant of losing a copy. Missense variants: 375 observed, 607.63 expected, observed/expected ratio (o/e) 0.62, 90% interval 0.57 to 0.67. Synonymous variants: 198 observed, 210.44 expected, observed/expected ratio (o/e) 0.94, 90% interval 0.84 to 1.06.
Homologues: Orthologues: macaque PTBP2 (100% identical), pig PTBP2 (100% identical), guinea pig PTBP2 (99% identical), mouse Ptbp2 (99% identical), rat Ptbp2 (99% identical), rabbit PTBP2 (99% identical), chimpanzee PTBP2 (94% identical), dog PTBP2 (94% identical), tropical clawed frog ptbp2 (91% identical), zebrafish ptbp2b (80% identical), zebrafish ptbp2a (76% identical), Drosophila melanogaster heph (53% identical), and 1 more. Paralogues in human: PTBP1 (75% identical), PTBP3 (68% identical), HNRNPL (28% identical), HNRNPLL (26% identical), RBM20 (22% identical).
Diseases named in the same sentence as PTBP2 in open-access papers:
PTBP2 is named in the same sentence as 56 diseases in open-access papers, as found by Europe PMC text mining. Sharing a sentence is not in itself a finding about the gene and the disease. The quoted sentences say what the papers report.
colorectal cancer (16 papers, 2015 to 2025). A primary or metastatic malignant neoplasm that affects the colon or rectum. "PTBP2 has been associated with oncogenic RNA splicing in various cancers, such as glioblastoma, osteosarcoma, and colorectal cancer." (PMID 40113750, 2025). "PTBP2 was also shown to stimulate the proliferation, migration, and metastasis of colorectal cancer cells." (PMID 36203873, 2022). "Promotes cellular proliferation, migration, and invasion via 1) binding to SFPQ and releasing oncogene PTBP2 from SFPQ/PTBP2 complex 2) increasing expression of AKAP-9 via promoting SRPK1-catalyzed SRSF1 phosphorylation in colorectal cancer cells." (PMID 27888635, 2017). "In colorectal cancer, instead, MALAT1/NEAT2 triggers tumor growth and metastasis by binding to the splicing factor SFPQ causing the subsequent disruption of the splicing regulator complex SFPQ-PTBP2 and the release of the oncogene PTBP2." (PMID 33799493, 2021). "MALAT1/SFPQ activates metastasis in colorectal cancer by releasing PTBP2." (PMID 33050646, 2020). "Colorectal cancer growth and metastasis could be promoted by the release of oncogene PTBP2 from the SFPQ/PTBP2 complex, which is achieved by the affinity between human metastasis-associated lung adenocarcinoma transcript 1 (lncRNA MALAT1) and SFPQ." (PMID 32429086, 2020). "In addition, HOTAIRM1 can interact with SFPQ in colorectal cancer (CRC) tissues that release PTBP2 from the SFPQ or PTBP2 complex." (PMID 30309340, 2018). "And PTBP2 be released by MALAT1 from the SFPQ/PTBP2 complex, thereby facilitating tumor growth and migration in colorectal cancer cells." (PMID 39830506, 2024). "MALAT1 can bind to SFPQ, resulting in the release of PTBP2 from the SFPQ/PTBP2 complex and promoting the growth and metastasis of colorectal cancer cells." (PMID 39532842, 2024). "In colorectal cancer, the binding of MALAT1 to SFPQ releases the PTBP2 oncogene from an SFPQ/PTBP2 complex, which promotes tumor growth and metastasis." (PMID 37444543, 2023). "Another study found that MALAT1 promotes colorectal cancer cell metastasis by competitively binding to PSF and releasing SFPQ from the SFPQ/PTBP2 (polypyrimidine tract binding protein 2) complex, which then increases the SFPQ-detached proto-oncogene PTBP2." (PMID 29416704, 2018). "Overexpressing PTBP2 increased its abundance by enhancing the utilization of its exon 10, which partially neutralized the repressive effect of elevated PTBP1 in colorectal cancer cells." (PMID 26857472, 2016). "PTBP2, a subtype of PTBP, exhibits differential tissue expression and is correlated with several types of cancer, including glioblastoma, osteosarcoma, and colorectal cancer." (PMID 40113750, 2025). "For example, metastasis associated with lung adenocarcinoma transcript-1 (MALAT1), a functional long non-coding RNA highly expressed in colorectal cancer cells, promotes cell proliferation and migration by binding to SFPQ, thus releasing PTBP2 from the SFPQ/PTBP2 complex." (PMID 35006436, 2020). "For example, In the investigation of colorectal cancer (CRC), MALAT1 could bind to SFPQ, thus releasing PTBP2 from the SFPQ/PTBP2 complex and the interaction between MALAT1 and SFPQ could be a novel therapeutic target for CRC35." (PMID 28623317, 2017). "In colorectal cancer, MALAT1 could disturb the stability of SFPQ/PTBP2 complex, and promote cell proliferation and migration." (PMID 26522444, 2015). "PTBP1 was frequently altered in colorectal cancer, pancreatic cancer, and ovarian cancer; PTBP2 was frequently altered in non-small cell lung cancer, lung cancer, and ovarian cancer; and PTBP3 was frequently altered in pancreatic cancer, soft tissue sarcoma, and colorectal cancer." (PMID 36203873, 2022).
neuroblastoma (7 papers, 2014 to 2025). Neuroblastoma (NB) is the most common solid, extracranial childhood tumor. "To further confirm the effects of KIS on PTBP2 activity, we used a fluorescent reporter that monitors in vivo AS in cultured neuroblastoma N2A cells." (PMID 38597390, 2024).
glioma (6 papers, 2018 to 2025). A benign or malignant brain and spinal cord tumor that arises from glial cells (astrocytes, oligodendrocytes, ependymal cells). "Knockdown of both PTBP1 and PTBP2 slowed glioma cell proliferation, and PTBP2 null mice died shortly after birth and exhibited misregulation of alternative splicing in genes involved in cytoskeletal remodeling and cell proliferation." (PMID 40113750, 2025). "It was discovered that reduction of PTBP1 and PTBP2 induced glioma cells to decrease proliferation and migration and to increase cell adhesion." (PMID 29936497, 2018). "Interestingly, SRSF3 is known to interplay with two other splicing factors, polypyrimidine tract binding protein 1 (PTBP1) and polypyrimidine tract binding protein 2 (PTBP2), that positively regulate glioma cells migration." (PMID 29415469, 2018). "SRSF3 has been shown to interact with two additional splicing factors, polypyrimidine tract binding protein 1 (PTBP1), and polypyrimidine tract binding protein 2 (PTBP2), which promote glioma cell motility." (PMID 35883576, 2022).
glioblastoma (5 papers, 2021 to 2025). The most malignant astrocytic tumor (WHO grade IV). "High PTBP2 expression was significantly associated with good survival of glioblastoma, rather than nephroblastoma, while high PTBP1 expression predicted unfavorable survival in both glioblastoma and nephroblastoma." (PMID 37040518, 2023). "Taken together, these findings demonstrate that SON overexpression in malignant gliomas, especially in GBM, has strong correlations with PTBP1 overexpression and PTBP2 downregulation, suggesting that there is a functional connectivity between SON, PTBP1, and PTBP2 in glioblastoma cells." (PMID 34548489, 2021). "Recent study featured sophisticated interplay of Ptbp1, Ptbp2, RbFox2, and SON (SON DNA and RNA binding protein) promoting glioblastoma multiforme (GBM) genesis." (PMID 35204777, 2022).
Obesity (4 papers, 2012 to 2022). Accumulation of substantial excess body fat. "We performed a mutation screen by Sanger sequencing in the PTBP2 gene in 192 female patients with (acute or recovered) AN and 191 children or adolescents with (extreme) obesity." (PMID 35680849, 2022). "A mutation screen of PTBP2 in 192 females with (acute or recovered) AN and 191 children or adolescents with (extreme) obesity revealed 25 variants." (PMID 35680849, 2022). "Our findings implicate many genes previously associated with obesity (e.g. PTBP2, TMEM18, MYT1L, POU3F2, SIM1, SH2B1), and also identified other potentially relevant candidates including TAS1R3, ALOX5AP, and GAS6." (PMID 29441128, 2018). "Thus, we performed a mutation screen of the PTBP2 gene in 192 females with AN (acute or recovered) and 191 children or adolescents with (extreme) obesity." (PMID 35680849, 2022). "In a recent study, the enriched expression level of the PTBP2 protein was found in patients with obesity compared to healthy individuals with normal body weight." (PMID 35680849, 2022). "The PTBP2 rs11165675 allele identified by GWAS in European adults failed to confer susceptibility to obesity in our study." (PMID 35295960, 2022). "However, the mechanism of PTBP2 regulating obesity remains unrevealed." (PMID 35295960, 2022). "Genotype distributions were not related to drop-out rates except for ETV5 and FAIM2, which had more completers among homozygotes than among non-carriers of the obesity risk-allele (P = 0.01 and 0.02 respectively), and for PTBP2, which showed the opposite pattern (P = 0.03)." (PMID 22952648, 2012). "The higher level of PTBP2 expression in patients with obesity compared to individuals without obesity suggested a role in obesity development." (PMID 35680849, 2022).
autism (3 papers, 2016 to 2021). Persistent deficits in social interaction and communication and interaction as well as a markedly restricted repertoire of activity and interest as well as repetitive patterns of behavior. "Interestingly, beside PTBP2, key regulators of alternative splicing, including the RBFOX1 family of proteins and SR100 are linked to neurodevelopmental disorders, including autism." (PMID 32327736, 2021).
progressive supranuclear palsy (3 papers, 2017 to 2021). A rare late-onset neurodegenerative disease characterized by supranuclear gaze palsy, postural instability, progressive rigidity, and mild dementia. "The upregulation of miR-132, which targets the 3′UTR of PTBP2, causes a decrease in PTBP2 expression, leading to a tau isoform imbalance, which is observed in progressive supranuclear palsy." (PMID 34769047, 2021). "miR-132 may also regulate tau alternative splicing in vitro by targeting poly-pyrimidine tract-binding protein 2 (PTBP2), and its levels correlate with tau splicing defects in patients with progressive supranuclear palsy (PSP) cases." (PMID 33833661, 2021).
Azoospermia (2 papers, 2017 to 2020). Absence of any measurable level of sperm,whereby spermatozoa cannot be observed even after centrifugation of the semen pellet. "Thus, our finding that Cracd was both over-expressed and then subsequently under-expressed in the less drastically affected Ptbp2 cKO testis of azoospermia mouse model, confirms its usefulness." (PMID 32962040, 2020). "Thus, we confirm that Ptbp2 is an essential factor in heat stress-induced sperm cell injury and non-obstructive azoospermia." (PMID 29045475, 2017). "To elucidate whether the changes in Ptbp2 expression are correlated with sperm cell injury and non-obstructive azoospermia in heat stress-affected testicular tissue, we investigated testicular tissues in a surgically-induced intraperitoneal cryptorchidism model in mice." (PMID 29045475, 2017).
Chronic Myeloid Leukemia (2 papers, 2025 to 2026). "In addition, PTBP2 has been shown to regulate survival and proliferation in Chronic Myeloid Leukemia, making it likely that PTPB2 at least partially compensates for PTBP1 loss in AML cells." (PMID 41214140, 2026).
colon cancer (2 papers, 2019 to 2023). "By performing RIP-qPCR assay in SW480 colon cancer cells, we found that PTBP1 indeed binds near this 3′ splice site, suggesting that PTBP1 directly represses Ptbp2 exon 10 inclusion in these cells." (PMID 36744439, 2023).
gastric cancer (2 papers, 2020 to 2021). A primary or metastatic malignant neoplasm involving the stomach. "Notably, CELF2, RBFOX2, PTBP2 and QKI were also involved in the misregulation of AS events in Epstein-Barr virus-associated gastric carcinomas." (PMID 33186122, 2020). "Conversely, in gastric cancer, the expression of CELF2, along with BAG2 (BAG Cochaperone 2), RBFOX2 (RNA Binding Fox-1 Homolog 20), and PTBP2 (Polypyrimidine Tract Binding Protein 2) splicing factors are associated with poor prognosis and alternative splicing events." (PMID 34681716, 2021).
lung carcinoma (2 papers, 2022 to 2023). "However, when PTBP1 was knocked down in lung cancer cells, PTBP2 levels went up to compensate for reduced PTBP1 levels, and PTBP2 interacts with NOVA1 and resulted in reduced FL TERT and telomerase." (PMID 37531400, 2023).
acute myeloid leukemia (1 paper, 2025). Acute myeloid leukemia (AML) is a group of neoplasms arising from precursor cells committed to the myeloid cell-line differentiation. "TF1 (human erythroleukemia), HEL (human erythroid leukemia), and F36P (MDS-RAEB) showed varying levels of PTBP2 expression, whereas HNT34 (BCR::ABL1+ human Acute Myeloid Leukemia) cells showed almost no PTBP2 expression among the four AML cell lines." (PMID 40113750, 2025).
behavioral disorders (1 paper, 2025). "Individuals with PTBP2 variants altering nucleocytoplasmic localization show nonsyndromic neurodevelopmental and behavioral disorders." (PMID 40965981, 2025).
bladder cancer (1 paper, 2025). "Thus, consistent with our findings, the knockdown of PTBP1 (which increases the level of PTBP2) has been reported to lead to autophagy in colorectal and bladder cancer." (PMID 40113750, 2025).
cortical atrophy (1 paper, 2023). "Ptbp2 knockout mice with Emx1-Cre-mediated conditional ablation of Ptbp2 in projecting neurons of the forebrain exhibit a series of neurodevelopmental abnormalities such as cortical atrophy appearing at P5 leading to postnatal lethality around P18-P2110." (PMID 37438340, 2023).
cryptorchidism (1 paper, 2017). The failure of one or both testes of a male fetus to descend from the abdomen into the scrotum during the late part of pregnancy. "Further experiments on the causal link between Ptbp2 and germ cell injury is required due to our insufficient knowledge regarding the etiology of cryptorchidism-induced infertility." (PMID 29045475, 2017). "Importantly, this study is the first to confirm the relationship between Ptbp2 and germ cell injury in cryptorchidism." (PMID 29045475, 2017). "To investigate whether changes in Ptbp2 expression are correlated with heat stress-induced germ cell injury in testicular tissue, we used a murine model of intraperitoneal cryptorchidism with surgical operation." (PMID 29045475, 2017). "And the Ptbp2 and Pgk2 mRNA levels were significantly decreased in parallel, leading us to conclude that the negative correlation between Ptbp2 levels and germ cell injury in unilateral cryptorchidism murine model." (PMID 29045475, 2017). "Despite the extensive studies focused on the function of Ptbp2 during spermatogenesis, no reports have been published on the behavior of Ptbp2 in idiopathic diseases of the reproductive system, especially cryptorchidism." (PMID 29045475, 2017). "Furthermore, it is important to note that we did not investigate the function of Ptbp2 in invitro germ cell and cryptorchidism patients, and we plan to do this in future research." (PMID 29045475, 2017).
developmental delay (1 paper, 2025). "Clinically, they exhibited developmental delay without skeletal dysplasia, consistent with mostly brain-restricted expression of PTBP2." (PMID 40965981, 2025).
Failure to thrive (1 paper, 2014). Failure to thrive (FTT) refers to a child whose physical growth is substantially below the norm. "The cause of the Ptbp2-EmxKO pups’ failure to thrive was apparent upon dissection of their brains." (PMID 24448406, 2014).
hepatoblastoma (1 paper, 2023). Hepatoblastoma (HB) is a malignant hepatic tumor and is the most common pediatric liver cancer. "In other pediatric tumors, PTBP2 was expressed at low levels in the metastasis and death cohorts of hepatoblastoma, whereas PTBP1 was highly expressed (GEO: GSE131329)." (PMID 37040518, 2023).
Intellectual disability (1 paper, 2023).
major depressive disorder (1 paper, 2022). An episode of depression lasting two or more weeks without an intervening episode of mania. "A recent case (AN) to case (major depressive disorder: MDD) GWAS detected rs720090 which is located in intron 9 of the PTBP2 gene (p value = 2 × 10−8)." (PMID 35680849, 2022).
malignant glioma (1 paper, 2021). A grade III or grade IV glioma arising from the central nervous system. "Our database analyses as well as immunostaining of human GBM samples showed that PTBP2 expression is decreased in malignant glioma." (PMID 34548489, 2021). "The ratios of PTBP2 exon 10 skipping/inclusion, INSR exon 11 skipping/inclusion (the ratio of INSR-A/INSR-B) and ECT2 exon 4 skipping/inclusion are indeed significantly increased in malignant glioma, especially in GBM patient samples when compared to normal brain." (PMID 34548489, 2021).
mental disorder (1 paper, 2025). A disease that has its basis in the disruption of mental process. "Furthermore, some of these genes (e.g., NEGR1, PTBP2, BCL11A, ARNTL, SLC25A12, ADARB1) were identified in a recent study investigating the genetic overlap between AN and mental disorders, further supporting their relevance to AN." (PMID 39971893, 2025).
myeloid leukemia (1 paper, 2025). A clonal proliferation of myeloid cells and their precursors in the bone marrow, peripheral blood, and spleen. "PTBP2 and its paralog, PTBP1, which plays a role in B-cell development, was found to be expressed aberrantly in myeloid leukemia." (PMID 40113750, 2025).
oral squamous cell carcinoma (1 paper, 2018). "It has been reported that SRSF3 regulates the expression of PTBP1 and PTBP2 in HEK-293 (human embryonic kidney epithelial cell) and CAL 27 (oral squamous cell carcinoma) cells." (PMID 30279379, 2018).
respiratory failure (1 paper, 2022). The significant impairment of gas exchange within the lungs resulting in hypoxia, hypercarbia, or both, to the extent that organ tissue perfusion is severely compromised. "Thus, Ptbp2 null mice display cyanosis and die immediately after birth due to respiratory failure." (PMID 35680849, 2022).
retinoblastoma (1 paper, 2025). A malignant tumor that originates in the nuclear layer of the retina. "Post-translational acetyl, phosphate, methyl and dimethyl modifications in PTBP2 incubated in splicing reaction mixtures containing WERI retinoblastoma nuclear extract." (PMID 40465779, 2025).
schizophrenia (1 paper, 2013). A major psychotic disorder characterized by abnormalities in the perception or expression of reality. "In fact, two genome wide association studies have reported the association of PTBP2 in European schizophrenia patients." (PMID 23936182, 2013).